E2F1 (E2F transcription factor 1)
Diseases named in the same sentence as E2F1 in open-access papers (continued):
Sharing a sentence is not in itself a finding about the gene and the disease.
cancer (continued). "The presence of binding sites for both the ER axis and E2F1 in many promoters of amplicon genes confirms the potential for regulation that could switch from ER dominant in luminal A cancers to E2F1 programs in luminal B cancers, or upon progression, when hormonal resistance develops." (PMID 32987805, 2020). "Interestingly, XBP1 negatively regulates transcription of Fbw7 via a feedback mechanism through NF-κB/E2F-1 axis signaling pathway, suggesting that overexpression of XBP1s may contribute to low level of Fbw7 expression in human cancers." (PMID 30783083, 2019). "This suggests that E2F1 may help cancer growth by promoting S phase entry." (PMID 31308377, 2019). "Also, deregulated expression of c-Myc and E2f1 is frequently found in cancer cells." (PMID 30060537, 2018). "Therefore, TRIM28 contributes to the negative regulation of E2F1 and may serve as a partial backup to prevent E2F1-mediated apoptosis in cancer cells, suggesting that TRIM28 acts as a pro-tumorigenic factor." (PMID 28851455, 2017). "Therefore, in the context of EBV infection, EBNA3C-mediated E2F6/E2F1 regulation may offer novel insights to further understand the important role of EBV latent antigens in E2Fs-related cellular functions or cancer development." (PMID 27548379, 2016). "In addition, we found that spinophilin might be involved in cancer stem cells, that the E2F-1 signaling is positively influenced and that DNA methylation in CRC cells might explain in part the differential expression of spinophilin in CRC." (PMID 25261368, 2014). "On the other hand, some reports have proposed that e2f-1 might suppress cancer cells." (PMID 24393368, 2014). "Also, E2F1 and p73 expression levels in the three concentrations of Kuding tea polyphenol treated cells were increased compared to those levels in untreated control cancer cells." (PMID 25100434, 2014). "Similarly our findings shed light on cancer cell lines demonstrating that E2F1 overexpression significantly enforced the capacity of cell migration and invasion, thereby enriching the understanding of this versatile transcription factor independent of apoptotic activity and proliferation trait." (PMID 24023875, 2013). "As such, scoring E2F1 positivity might be morestraightforward and reproducible, and further evaluation of E2F1 as a proliferationand prognostic marker in prostate and other cancer types is warranted." (PMID 21629784, 2011). "We demonstrated that E2F1 bound to the potential transcriptionally important CpG sites in RASSF1A gene of a normal lung cell line expressing RASSF1A transcripts, whereas loss of E2F1 binding to RASSF1A in A549 cancer cell line was the result of DNA methylation." (PMID 20877461, 2010). "Therefore, it appears that telomerase suppression in SEG- 1 cancer cells leads to induction of p73, p63 and E2F1, which may up-regulate p21 leading to cell cycle arrest and senescence." (PMID 16022731, 2005). "The loss of this Rb-E2F1 apoptotic pathway may well explain why mice lacking E2F1 are predisposed to cancer." (PMID 12107831, 2002). "We showed here that the presence of distinct E2F1 activity, which activates EREA and ERE73, enables the discrimination of cancer cell lines from normal growing cells." (PMID 41511373, 2026).
cancer (continued). "Based on clinical data from TCGA, we recently demonstrated that increased levels of E2F1, STAT3, and IL6, impacting cancer stemness and progression, correlate with CD4+ T helper type 2 (Th2) infiltration, while blocking Th1 in primary and metastatic melanoma." (PMID 40299510, 2025). "In this regard, our previous studies demonstrated that CTL-mediated immune selection enriches immune-refractory cancer cells with CSC-like properties and resistance to CTL-mediated apoptosis, driven by E2F1 through FGFR signaling or NANOG induction." (PMID 41339438, 2025). "While we have established that the E2F1-HMGCR axis drives ferroptosis resistance, this raises an important question: how is E2F1 upregulated during cancer immunoediting?" (PMID 41339438, 2025). "E2F1 promotes EXOSC10 transcription and then facilitates HCC growth and cancer stemness, revealing a potential target for HCC therapy." (PMID 40221814, 2025). "In Saos-2 cells, the ERE73 (1 + 2)-ARF (−13) and ERE73 (3 + 4)-ARF (−13) promoters exhibited higher cancer cell specificity than that of the hTERT, ARF, or E2WT-ARF (−13) promoters, and even exceeded that of the E2F1 promoter." (PMID 41439972, 2025). "For other genes, the proportion changes in different cell types expressing BIRC5, CDK1, AURKA, E2F1, and KIF2C are remarkably similar to the overall proportion changes in different cell types during cancer progression." (PMID 39859485, 2025). "In conclusion, this study first confirmed that E2F1 up-regulated EXOSC10 expression by promoting its transcription, thereby enhancing HCC growth and cancer stemness." (PMID 40221814, 2025). "Using the online tool GEPIA, we subsequently screened out four transcription factors (ETV4, FOXP3, E2F1 and XBP1) which are highly expressed in CRC and closely related to cancer." (PMID 38041531, 2024). "Using this system, ARF-TK was a more specific inducer of cell death in cancer cells compared to E2F1-KT: ARF-TK showed lower cytotoxicity than E2F1-TK in normal human fibroblasts, but comparable cytotoxicity to E2F1-TK in cancer cells." (PMID 36833320, 2023). "In our previous study, we found that UBE2C was co-regulated by lysine acetyltransferase 2A (KAT2A) and E2F transcription factor 1 (E2F1) to promote cell proliferation and migration in pan-cancer." (PMID 37958642, 2023). "The expression of 5-lipoxygenase, the key enzyme in leukotriene biosynthesis, is suppressed in proliferating cancer cells by a PI3K/mTORC-2– and MEK-1/ERK-dependent axis involving E2F1 and b-Myb." (PMID 36849252, 2023). "By referring to related literatures and databases, E2F1, GLI1, CDK3, and Mcm4, as candidate target genes, were found to be closely related to the occurrence of cancers, which was very helpful to clarify the mechanism of EZH2 in PC." (PMID 37198697, 2023). "ASPH, CDKN2A, E2F1, P3H1, and PTTG1 were identified as prognostic indicators of unfavorable outcomes within multiple cancer types." (PMID 37497116, 2023). "Further study showed that RP11-19E11.1 can directly interact with TF E2F Transcription Factor 1 (E2F1), which is essential for inhibiting the DNA damage response and apoptosis and maintaining cancer cell proliferation and survival." (PMID 36750826, 2023).
cancer (continued). "The results showed that higher E2F1 level was significantly correlated with unfavorable OS and DFS in cancer patients." (PMID 37277745, 2023). "increased expression of downstream genes of E2F1 such as OCT4 and SOX2 maintain cancer cell stemness." (PMID 38028543, 2023). "Low expression of RBBP4 no longer inhibits E2F1, allowing for increased expression of downstream genes of E2F1 such as OCT4 and SOX2 that maintain cancer cell stemness." (PMID 38028543, 2023). "Of note, circ_63706 knockdown downregulated genes contributing to important cancer pathways including RBBP4, TGFA, E2F1, and HRAS." (PMID 36899402, 2023). "E2F1 and CHEK2 were highly expressed across most cancer types compared to normal samples, while PDK4 and NTRK2 were decreased in various cancers." (PMID 36937870, 2023). "Among the tumorigenesis-associated genes, KEGG analysis revealed that the upregulated genes, including SLC7A5, E2F1, HIF1A, VEGFA, and EGFR, were predominantly related to central carbon metabolism in cancer, the cell cycle, and the HIF-1 signaling pathway." (PMID 37328520, 2023). "SCNV gain was identified in several genes such as E2F1, ASPH, BLVRA, and CEBPB across multiple cancers." (PMID 37497116, 2023). "Normal human fibroblasts and several cancer cell lines were infected with the viruses, and in the presence of ganciclovir, cytotoxicity was compared between ARF and the E2F1 promoter." (PMID 36833320, 2023). "Activities of E2F1 and ARF promoters were compared between normal human fibroblasts and several cancer cell lines." (PMID 36833320, 2023). "However, the mechanism of how E2F1 mediates EMT in cancer remains largely unknown." (PMID 37160894, 2023). "As for the downregulated DEGs, the top TFs were E2F4/DP1, E2F1/DP2, E2F4/DP2, and E2F1/DP1, which are members of the E2F transcription factor family known to be involved in cell cycle control and cancer progression." (PMID 38057925, 2023). "In all of the cancer cell lines tested, ARF promoter activity showed higher cancer-cell specificity than the E2F1 promoter." (PMID 36833320, 2023). "Taken together, these reports indicated that KAT2A, E2F1, and UBE2C play a fundamental role in the progression of several types of cancers." (PMID 36292703, 2022). "Although the relevance of MXI1 to cancer metastasis remains unexplored, our data, together with the previous observations that MYC and E2F1 promote epithelial-mesenchymal transition and metastasis, implicate MXI1 in metastasis-suppression." (PMID 35149728, 2022). "We selected five genes (P57, CDK1, CDH2, E2F1 and BIK) that are quite relevant to cancer cell proliferation and apoptosis 24-28." (PMID 35371316, 2022). "Both E2F1 and E2F3, as oncogenes, are involved in the regulation of many biological properties, such as cancer stemness and apoptosis." (PMID 36175803, 2022). "E2F1 and CKS2 were both highly expressed in 21 cancer types and such positive correlation was also observed in our RB clinical data." (PMID 36096885, 2022). "Transcription factors, including Sp1, AP-2, BRCA, E2F1 and MYBL2, bind to the DNA sequence in the promoter region of RRM2 and regulate their expression in response to DNA damage in cancer cells." (PMID 35651787, 2022). "For example, CDKN2A, E2F1, E2F2, and CDK4 were significantly overexpressed in 28, 26, 24, and 15 cancers, respectively." (PMID 35911954, 2022). "Therefore, DSF/copper could be a potential drug for cancers with c-Myc or E2F1 overexpression." (PMID 36362068, 2022). "Therefore, we propose a new clinical framework defined by the network that a lncRNA-GAS5 functioning as an inhibitor of E2F1 may inhibit cancer progression through the establishment of miR-34c and can induce cell cycle arrest and apoptosis at the G1/S checkpoint." (PMID 36316351, 2022). "We observed that the methylation of SRGs in diverse cancers was found to be highly heterogeneous, and only E2F2 (n = 11) and E2F1 (n = 9) exhibited hypomethylation in most cancers." (PMID 35911954, 2022).
cancer (continued). "During DNA damage response in cancer cells, TFDP3 is induced and can inhibit E2F1-mediated apoptosis." (PMID 34745961, 2021). "Some of these TFs have been shown to exhibit oncogenic properties in various types of cancers, such as ESR1, FOXA1 and E2F1 60–62." (PMID 33850167, 2021). "Among 12 genes reported in the literature as SL with RB1 6 genes (PPWD1, SKP2, AURKA, AURKB, E2F1, and E2F3) scored as SL RB1 partners in human cancer patients." (PMID 33591981, 2021). "Recent literature has indicated that the expression of HMGB2 is elevated in various human cancers, suggesting that the small heterodimer partner represses HMGB2 by recruiting or repressing E2F1 activity." (PMID 34408262, 2021). "The genes involving cell cycle control, DNA replication, apoptosis, senescence and autophagy in cancer pathways including CDK4, E2F1, Bax, CDKN1A, GADD45A, FAS, GABARAPL2, and SQSTM were significantly upregulated." (PMID 34305605, 2021). "ETC-168 can be used as a useful compound and surrogate tool to block oncogenic expression of E2F1, FOXM1, and WEE1 in human cancers." (PMID 33564073, 2021). "Surprisingly, BCL2L1, E2F1, HRAS, MAPK8, MITF, RELA, and SP1 were all found in the mitophagy and cancer pathways." (PMID 34262589, 2021). "E2F1, E2F2 and E2F7 proteins, which were upregulated in most of the cancer types and appear as high centrality nodes in the bipartite graphs, regulate around 224, 93 and 74 high centrality genes, respectively." (PMID 34728699, 2021). "As both FOXM1 and E2F1 are master transcription factors in human cancer, inhibition of MNK1/2-dependent expression of FOXM1 and E2F1 will have a broad impact on transcriptome." (PMID 33564073, 2021). "Nevertheless, genomic amplification is not the only mechanism responsible for the increased PLANE expression in cancer cells, rather, PLANE upregulation is more commonly driven by E2F1-mediated transcriptional activation." (PMID 34145290, 2021). "E2F transcription factor 1 (E2F1) is reputed as a key transcription factor and regulates cell-cycle progression in cancers." (PMID 31934717, 2020). "Few transcription factors, such as E2F1 and E2F3, have been shown to activate RRM2 gene transcription in cancer cells." (PMID 31936661, 2020). "We found that the expression of E2F1, a member of E2F protein family, was positively correlated with DDX11 mRNA expression in most cancer types." (PMID 32332880, 2020). "The results indicated that some crucial cancer-related pathways were related to the high expression of CXCL8 and E2F1 and the low expression of CYP2C8, which was consistent with the expression level results and prognostic results." (PMID 32851080, 2020). "Recently, emerging evidences have shown that E2F1 and CCND1 are involved in chemoresistance of various cancers." (PMID 32796817, 2020). "In all analyzed cancer cells, IGF2BP1 depletion significantly reduced E2F1–3 mRNA levels, with the exception of A549 cells where E2F3 transcripts were modestly elevated." (PMID 32761127, 2020). "In this study, we investigated the correlation between E2F1 and RAD54L and the effect of such correlation on cancer progression." (PMID 33261027, 2020).
cancer (continued). "The results showed that the mRNA levels of E2F1, E2F2, E2F3, E2F5, E2F7 and E2F8 were significantly lower in adjacent tissues compared with those in carcinoma tissues." (PMID 32117628, 2020). "In accordance with the mRNA expression levels obtained from GEPIA, the protein expression of E2F1, E2F2, E2F3, E2F5, E2F7 and E2F8 were significantly higher in carcinoma tissues." (PMID 32117628, 2020). "It is worthwhile to note that only FOXM1, E2F1, and RAD51 showed positive correlations with UBE2C in all 27 cancers." (PMID 31067633, 2019). "In addition, E2F1 may independently serve as a biomarker or novel gene target for cancer therapy." (PMID 31534120, 2019). "Altogether, our data show that EZH2 cooperates with E2F1 to stimulate expression of genes involved in ACC aggressiveness and establishes RRM2 as an interesting therapeutic target in this cancer." (PMID 31363169, 2019). "Combining RNA-RNA interaction prediction and transcription regulatory networks, we identified E2F1, FOXM1 and PVT1 regulatory path as recurring pan-cancer regulatory entity." (PMID 30809433, 2019). "From our network, we observed that E2F1 regulates POLD1, ASF1B, FOXM1 and RACGAP1 which are up-regulated in all 15 cancer types (Subnetwork)." (PMID 30809433, 2019). "HBXIP is found highly expressed in breast cancer and it generally regulates the expression of genes involved in cancer growth and metastasis interacting with different transcription factors (TF-II, STAT3, E2F1, SP1, and c-Myc)." (PMID 30866496, 2019). "Previous research has shown that Smad2/3 and E2F1 are critical mediators of the effects of TGF-β in both normal and cancer cells." (PMID 32010624, 2019). "KIF2C and KIF20A were reported, in a study based on ChIP-chip assays, as the target of E2F family including E2F1, E2F4, and E2F6 in normal and cancer cells of breast tissue." (PMID 30813560, 2019). "A common single-nucleotide polymorphism (SNP) in the TERT promoter, rs2853669 (c.-245A>G), previously studied in several cell lines and cancer cohorts, has been suggested to alter promoter-mediated TERT expression by impacting E2F1 or ETS/TCF binding." (PMID 31395865, 2019). "Since it has been demonstrated that Smad2/3 and E2F1 are critical mediators of TGF-β-induced EMT in both normal and cancer cells, we examined the effects of TGF-β1 and miR-20b-5p on Smad2 phosphorylation and E2F1 expression." (PMID 32010624, 2019). "Analyzing the interplay, we have zeroed in on E2F1, FOXM1 (transcription factors) and PVT1 (lncRNA) regulatory path as recurring pan-cancer regulatory entity." (PMID 30809433, 2019). "Among the top 10 DRGs identified from TCGA-STAD dataset, six are GC related (E2F1, AK1B10, CEBPA, PTK7, RASAL1, GKN), and three are cancer related (DPCR1, GGT6, RAB25)." (PMID 29745833, 2018). "We deduced that selective arresting of c-MYC promoter via stabilizing G-quadruplex activates a unique crosstalk with E2F-1 and VEGF-A, that concomitantly reduces BCL-2 expression triggering apoptosis in cancer cells." (PMID 30239898, 2018). "Slightly fewer proteins (10.8%) were uniquely bimodal only at the protein level, including important cancer-related proteins such as MEK1, mTOR, E2F1, TTF1, EIF4G, and JAB1." (PMID 29293502, 2018). "It regulates genes associated with cell proliferation (cyclin D, cyclin E, Cdk2, E2F-1, c-Myc), metastasis (VEGF), and apoptosis (survivin, XIPA), all of which contribute to the hallmarks of cancer." (PMID 28099934, 2017). "E2F transcription factor 1 (E2F1) and E2F transcription factor 8 (E2F8) are upregulated in many cancers and stimulate UHRF1 expression by directly binding to different sites in its promoter region." (PMID 28881702, 2017). "E2F transcription factor 1, also known as E2F1, has been widely studied in the generation and progression of several cancers." (PMID 28316892, 2017). "CIP2A was previously shown to block PP2A activity leading to enhanced cancer cell signaling such as those mediated by Akt, MYC and E2F1." (PMID 28884018, 2017).